GNB3 (G protein subunit beta 3)
Diseases named in the same sentence as GNB3 in open-access papers (continued):
Sharing a sentence is not in itself a finding about the gene and the disease.
Hypertension (continued). "This in turn could be one of the underlying reasons why GNB3 825T individuals are predisposed to hypertension." (PMID 21887213, 2011). "Taken together, our overall associations suggested null association of α-adducin G460T and GNB3 C825T polymorphisms with hypertension in Chinese, whereas we locally indentified marginal significance for C825T, as a putative salt-sensitive switch, in southern Chinese." (PMID 21364877, 2011). "Finally, we determined the effect of ecological factors and hypertension susceptibility, as measured by the GNB3 825T allele frequency, on worldwide variation in blood pressure." (PMID 16429165, 2005). "Likewise, GNB3 825T represents a number of functional alleles that influence hypertension susceptibility." (PMID 16429165, 2005). "Consistent with this hypothesis, latitude and hypertension susceptibility as determined by the presence of the GNB3 825T allele explains a large portion of worldwide variation in blood pressure." (PMID 16429165, 2005). "A C3T polymorphism at nucleotide 825 in exon 10 of the G protein β3 subunit gene (GNB3/C825T) was demonstrated to be associated with enhanced intracellular signal transduction and a variety of cardiovascular risk factors, including hypertension, obesity, dyslipidaemia, diabetes, and atherosclerosis." (PMID 31185929, 2019). "Furthermore, the study tested the hypothesis that possible joint effects of GNB3 and dietary sodium intake on the risk of hypertension is remarkable comparing their independent effects." (PMID 29848945, 2018). "Guanine nucleotide binding protein beta-3 (GNB3) variants C825T and Ser275Ser(M/N) [rs5443] may be associated with hypertension elevation responsible for decreased longevity, and GNB3 may be implicated in obesity, coronary artery disease, left ventricular hypertrophy, and diabetes mellitus." (PMID 24376503, 2013). "Likewise, GNB3 presents a number of functional alleles that influence hypertension susceptibility." (PMID 23799054, 2013). "GNB3 TT genotype was related to the development of hypertension with an adjusted odds ratio of 1.21 (95% CI 0.85–1.74), comparing with CT + CC genotype." (PMID 29848945, 2018). "Our results provide a strong gene–sodium interaction between GNB3 C825T and dietary sodium intake on the development of hypertension." (PMID 29848945, 2018). "The determinants of hypertension were three genotypes of SNP in GNB3 (TT; CT; and CC) and two dietary salt categories on the basis of the level of sodium consumption representing high (>4800 mg/day) and low-sodium (<2400 mg/day) diets." (PMID 29848945, 2018). "As already emphasized, our main aim was to investigate the role of FTO and GNB3 in EH; we adjusted all the results with BMI and other possible confounders to ascertain the direct effect of these genes on hypertension regulation." (PMID 23691120, 2013). "GNB3 C825T and ACE I/D polymorphisms have also been linked with hypertension and other vascular dysfunctions in aging Korean patients." (PMID 24376503, 2013). "While the GNB3 variant has also been associated with phenotypes such as tumor progression, drug response [75,76, and stroke, some studies do not find that haplotypes formed by common GNB3 polymorphisms contribute to the development of hypertension and obesity." (PMID 39743506, 2025). "They indicated that GNB3 C825T polymorphism did not have a major effect on the pressor response to salt in hypertension." (PMID 29848945, 2018). "Participants with GNB3 TT genotype had more than 21% increased risk of developing hypertension, but this was not statistically significant." (PMID 29848945, 2018). "Although our single locus results on FTO and GNB3 were encouraging, however, in a polygenic and multifactorial disease like hypertension, the magnitude of effect is bound to be missed if the genes are examined individually and without considering potential interactions." (PMID 23691120, 2013).
Hypertension (continued). "In the cumulative meta-analysis, three models showed evidence of a non-association between GNB3 alleles and hypertension or stroke." (PMID 23799054, 2013). "But, the GNB3 C825T polymorphism failed to contribute to the risk of stroke, thus it was clear that the polymorphism contributed to hypertension and stroke differently." (PMID 23799054, 2013). "Generally, the GNB3 825T allele was only slightly associated with an increased risk of essential hypertension compared to non-carriers." (PMID 23799054, 2013). "Furthermore, a latitudinal cline was identified both for the allele frequencies of the SNPs associated with hypertension (CYP3A5, AGT, GNB3), as well as for those associated with the ability to taste phenylthiocarbamide (TAS2R38)." (PMID 18248681, 2008). "Downregulation of genes such as GNB3, SENP2, and YTHDC2 highlights potential links to hypertension, early mortality, and male fertility issues." (PMID 38681774, 2023). "No previous studies have reported an association of the GNB3 and ACE polymorphisms with hypertension and preeclampsia, specifically in the PPCM population." (PMID 37089887, 2023).
Obesity (25 papers, 2009 to 2026). Accumulation of substantial excess body fat. "Although the GNB3 C825T polymorphism is often linked to obesity and increased hypertension, it is also considered a potential candidate gene for physical performance." (PMID 40055285, 2025). "Studies regarding the role of GNB3 rs5443 polymorphism in the development of obesity and its related comorbidities are contradictory." (PMID 34055005, 2021). "Regarding GNB3 rs5443 polymorphism, the likelihood of obesity was linked to the TT genotype which was also associated with increased leptin levels." (PMID 29937877, 2017). "The T allele of GNB3 rs5443 SNP has been reported to predispose to obesity in German, Chinese and South African populations." (PMID 29937877, 2017). "Several epidemiological studies have shown an association between the GNB3 825T allele and other features of metabolic syndrome, including obesity, insulin resistance, changes in autonomic nervous function, and dyslipidemia." (PMID 23799054, 2013). "The homozygous T allele carriage of the GNB3 C825T is associated with obesity, but somehow has an opposite effect on the onset of AMI among our studied population." (PMID 22408428, 2012). "In conclusion, TNF-α-308G/A and the GNB3 C825T polymorphisms are associated with obesity and AMI in the Taiwanese population." (PMID 22408428, 2012). "An association between the T homozygosity of GNB3 C825T polymorphism and obesity was also observed (Fisher’s exact, p = 0.009)." (PMID 22408428, 2012). "Although the GNB3 gene is known to be involved in lipid metabolism and fat cell differentiation, studies have shown inconsistent associations between a common single nucleotide polymorphism of GNB3 (c.825C > T, rs5443) and obesity across different populations." (PMID 41799029, 2026). "The GNB3 splice variant increases vascular reactivity and obesity-related HTN." (PMID 41573461, 2025). "The protein subunit encoded by the GNB3 (guanine nucleotide-binding protein beta-3) gene is regarded as a crucial regulatory factor for signal transduction receptors and effectors, with reports indicating a significant association with obesity." (PMID 39519268, 2024). "The polymorphism of FTO gene rs17817449 and GNB3 gene rs5443 (C825T) may be a genetic determinant of obesity in Saudi population, whereas impact of MC4R Asn274Ser change could not be detected in our sample." (PMID 29937877, 2017). "The polymorphism of FTO gene rs17817449 and GNB3 gene rs5443 (C825T) may be a genetic determinant of obesity in Saudi population whereas impact of MC4R Asn274Ser change could not be detected." (PMID 29937877, 2017). "Genotyping at the TNF-α and GNB3 loci represents an ideal tool for preventive medicine, in that individuals at risk of obesity and AMI can be identified early and their genetic predisposition could be counteracted through changes in lifestyle." (PMID 22408428, 2012). "Excluding the influence on blood pressure control, many studies examined the potential association between GNB3 C825T polymorphism and several other phenotypes of clinic traits, such as obesity, atherosclerosis, myocardial infarction, radial artery hypertrophy, and diabetes." (PMID 22408428, 2012). "The T homozygosity of the GNB3 C825T polymorphism results in a transcriptional truncated variant, and through the signal-enhancing ability of the G protein, it modulates adipogenesis and obesity risk." (PMID 22408428, 2012). "The 825 T allele of the GNB3 gene is associated with an increased BMI across different ethnicities, and apparently represents a "thrifty genotype".20,21 Several studies, have reported a significant relationship between the GNB3 825C/T polymorphism and obesity or fat metabolism." (PMID 20046372, 2009). "The results revealed that 18 of the DMR genes were associated with addiction and obesity (ADCY3; ADCY9; ATF4; CDK5R1; CHRNB2; GABRD; GABRG3; GNB1; GNB3; GRK5; HDAC4; HDAC9; MAP2K1; PDE11A; PDE2A; PDE3A; PPP1CA; SLC6A3)." (PMID 34389046, 2021).
Obesity (continued). "GNB3 is the most widely studied G-protein in various disease processes including depression, cardiovascular disease, obesity, and irritable bowel syndrome." (PMID 31178907, 2019). "The aim of this study was to evaluate the association of the FTO rs17817449 (G>T), GNB3 rs5443 (C825T) and MC4R Asn274Ser (A822G) gene polymorphism with obesity and obesity-related metabolic traits in Saudi subjects." (PMID 29937877, 2017). "In the current study, we explored the association of FTO rs17817449 (G>T), GNB3 rs5443 (C825T) and MCR4 (A822G) genes SNP with obesity and obesity-related metabolic traits in a small sample of Saudi population." (PMID 29937877, 2017). "In addition, GNB3 overexpression leads to obesity and glucose intolerance in mice and produces a series of metabolic syndromes such as acute thermogenic dysregulation." (PMID 36230385, 2022). "For example, the adrenergic receptor beta-2 (ADRB2), adrenergic receptor beta-3 (ADRB3), guanine nucleotide-binding protein (GNB3), uncoupling protein 1 (UCP1), and fat mass- and obesity-associated (FTO) genes are all reported to have associations with obesity." (PMID 34055005, 2021). "The significance of FTO rs17817449, GNB3 rs5443 and MC4R gene mutation in Saudi obese populations has not been examined despite its association with obesity in other parts of the world." (PMID 29937877, 2017). "However, no previous studies have reported an association of the GNB3 and ACE gene polymorphisms with obesity in the PPCM population." (PMID 37089887, 2023). "In this study, the GNB3 TT genotype was more frequent in obese subjects, males or females, the frequency was (62.7% and 83.6%) versus (21.4% and 20%) respectively, in non-obese subjects suggesting the possible relation with obesity." (PMID 29937877, 2017). "However, in the case of miR‐150:GNB3, miR‐506:GNB3, and miR‐124:GNB3, only miR‐124 and miR‐506 were associated with CRC, suggesting that this interaction may not be effective in CRC and obesity." (PMID 36301024, 2022).
diabetes (12 papers, 2008 to 2022). "The GNB3 gene polymorphisms, including C825T, have been linked to type 2 diabetes mellitus and its complications." (PMID 32290826, 2020). "Studies found that the GNB3 C825T variant is a risk factor for hypertension, obesity, metabolic syndrome, atherosclerosis and diabetes." (PMID 28330327, 2016). "The final multivariate analysis showed that the TT genotype of GNB3 exerted a moderate effect on the risk of development of acute PAOD after transplant (relative risk, 2.4; p = 0.05) when compared with pretransplant diabetes mellitus as an independent risk factor." (PMID 36077181, 2022).
depression (9 papers, 2016 to 2025). "Out of these proteins, GNB3 is a serotonin-related gene, whose polymorphism was reported to be associated with depression in a meta-analysis." (PMID 27025271, 2016). "Studies have shown that the Gnb3 gene is related to the occurrence of neurological diseases, such as depression and dementia." (PMID 38338822, 2024). "By integrating data from the literature, we revealed 4 genes of interest (GNB3, CNR1, MTHFR, and NCAM1) that were likely to be associated with the aetiology of both MI and depression." (PMID 31185929, 2019). "In conclusion, using literature mining methods, the GNB3, CNR1, MTHFR, and NCAM1 genes were identified and directly or indirectly implicated in the regulation of MI and depression." (PMID 31185929, 2019). "In the present study, we found the highest GNB3 expression in the heart ventricle and cingulate cortex of the brain, which was in accordance with the aetiology of depression." (PMID 31185929, 2019). "Thus, further study of GNB3 is essential for assessment of the interaction between MI and depression." (PMID 31185929, 2019). "GNB3, CNR1, MTHFR, and NCAM1 are putative new candidate genes that may influence the interactions between MI and depression, and may represent potential targets for therapeutic intervention." (PMID 31185929, 2019). "Taken together, these results suggest that the overexpression of the GNB3, CNR1, MTHFR, and NCAM1 genes may contribute to the development of MI and depression and may play a role in the interaction between these two diseases." (PMID 31185929, 2019).
metabolic syndrome (7 papers, 2008 to 2023). A cluster of metabolic risk factors for CARDIOVASCULAR DISEASES and TYPE 2 DIABETES MELLITUS. "Genetic effects, such as GNB3, and environmental factors, such as smoking and education level, may contribute to the risk for metabolic syndrome in BD." (PMID 36077028, 2022). "In our transgenic model, GNB3 overexpression is associated with obesity, type 2 diabetes, and metabolic syndrome that presents without hyperphagia or reduced locomotion." (PMID 29206867, 2017).
COVID-19 (4 papers, 2022 to 2025). A disease caused by infection with severe acute respiratory syndrome coronavirus 2. "Despite these promising insights, further research is needed to elucidate the mechanistic pathways linking GNB3 variants to immune modulation and to determine their potential role in shaping clinical outcomes in COVID-19." (PMID 40543387, 2025). "From 11 March 2020 to 30 June 2021, we enrolled and studied 1,570 SARS-CoV-2-positive patients to determine the association of the SNP rs5443 in the gene GNB3, with severity of COVID-19." (PMID 36017493, 2022). "The SNP rs5443 in the gene GNB3 was not only correlated to higher T cell responses but also to a significantly reduced risk for COVID-19 fatality in our study in univariate and multivariable analyses." (PMID 36017493, 2022). "Here, we investigated whether genotypes of the c.825C>T polymorphism in the gene GNB3 (rs5443) may influence the immune response after vaccination against COVID-19." (PMID 36105097, 2022). "In this study we could show that the TT genotype of the SNP rs5443 in the gene GNB3 is associated with protection against COVID-19 fatality." (PMID 36017493, 2022). "Together with a younger patient age, a normal white blood cell count at hospital admission, the GNB3 rs5443 TT genotype remained an independent protective factor against COVID-19 fatality in our study." (PMID 36017493, 2022). "In light of these observations, we hypothesized that the SNP rs5443 in the gene GNB3 might influence the T cell response in COVID-19 patients as well and, thereby, the outcome of the disease." (PMID 36017493, 2022). "Although we observed a significant association of the factors described previously in univariate analysis, only a younger age of the patients, normal blood cell counts, and the GNB3 rs5443 TT genotype remained independent predictors against COVID-19 fatality in multivariable analysis." (PMID 36017493, 2022). "To answer this question we analyzed the SNP rs5443 in the gene GNB3 in a comprehensive retrospective German cohort with SARS-CoV-2 infection and its influence upon T cell response and course of COVID-19." (PMID 36017493, 2022). "GNB3 rs5443 (c.825C>T) genotype distribution among all patients with SARS-CoV-2 infection and subdivided according to the severity of COVID-19." (PMID 36017493, 2022).
myocardial infarction (4 papers, 2012 to 2023). Gross necrosis of the myocardium, as a result of interruption of the blood supply to the area, as in coronary thrombosis. "A multivariate analysis showed that homozygous GNB3 c.825C>T polymorphism exerted only a mild effect for the occurrence of myocardial infarction (relative risk, 2.2; p = 0.065) or acute PAOD (relative risk, 2.4; p = 0.05) after renal transplant." (PMID 36077181, 2022).
Stroke (4 papers, 2013 to 2025). Sudden impairment of blood flow to a part of the brain due to occlusion or rupture of an artery to the brain. "No statistical evidence of publication bias was identified regarding the GNB3 C825T polymorphism and its association with stroke." (PMID 23799054, 2013). "But, considering that most of the included stroke patients were Asian, our results cannot be directly used to extrapolate a correlation between the GNB3 c825T polymorphism and stroke in Caucasians, Africans, or other ethnicities." (PMID 23799054, 2013). "The main characteristics of the included studies regarding association between the GNB3 C825T polymorphism and stroke." (PMID 23799054, 2013). "Only one publication regarding Caucasians was screened in an analysis of the association between the GNB3 C825T polymorphism and stroke, and all of the control sources were population-based, thus we did not perform subgroup analysis by ethnicity." (PMID 23799054, 2013). "Finally, the number of stroke cases were limited and had relatively weak statistical power to detect potential risks of the GNB3 C825T polymorphism." (PMID 23799054, 2013). "The main results of meta-analysis of association between the GNB3 C825T polymorphism and stroke." (PMID 23799054, 2013). "However, none of the comparison models found an association between the GNB3 C825T polymorphism and stroke (allelic model: OR = 1.11, 95% CI = 0.94–1.32; dominant model: OR = 1.16, 95% CI = 0.92–1.48; and recessive model: OR = 1.05, 95% CI = 0.97–1.14, respectively)." (PMID 23799054, 2013).
type 2 diabetes mellitus (4 papers, 2016 to 2022). A type of diabetes mellitus that is characterized by insulin resistance or desensitization and increased blood glucose levels. "Furthermore, increased fasting plasma glucose levels were detected in Japanese patients suffering from diabetes mellitus type II and having the rs2301339 polymorphism of GNB3." (PMID 36077181, 2022). "Taken together, our study provides the first functional link between GNB3 and obesity, and presents insight into novel pathways that could be applied to combat obesity and type 2 diabetes." (PMID 29206867, 2017).
heart failure (3 papers, 2017 to 2025). Inability of the heart to pump blood at an adequate rate to meet tissue metabolic requirements. "A genetic association study has demonstrated a pathophysiological association between the genetic locus rs5443 (Gnb3) and ventricular remodeling in heart failure." (PMID 38089628, 2023).
left ventricular hypertrophy (3 papers, 2013 to 2023). Enlargement of the LEFT VENTRICLE of the heart. "Numerous studies have ruled out the GNB3 c.825C > T polymorphism as an essential risk factor for the development of left ventricular hypertrophy." (PMID 37894940, 2023).
migraine (3 papers, 2021 to 2025). "Genetic variants in genes such as SLC6A4 (SERT), DRD2 (dopamine receptor), PRDM16 or CYP1A2, and GNB3 have been associated with a modified therapy outcome with triptans in migraine and cluster headache, respectively." (PMID 35222013, 2021).